SF3B1 (splicing factor 3b subunit 1)
Diseases named in the same sentence as SF3B1 in open-access papers (continued):
Sharing a sentence is not in itself a finding about the gene and the disease.
thrombosis (2 papers, 2022 to 2024). "In a Mayo Clinic cohort comprising 82 RARS-T patients, multivariable analysis of thrombosis-free survival revealed that the presence of SF3B1 mutations independently predicted inferior thrombosis-free survival; however, the underlying mechanism involved remains unclear." (PMID 38714876, 2024). "Comparison of MDS/MPN-RS-T (n = 158) and MDS/MPN-U with BM RS ≥ 15% (MDS/MPN-U-RS; n = 25) did not reveal significant differences in frequency of thrombosis, OS, or LFS, although SF3B1 mutation frequency was higher in the former (93% versus 59%; P = 0.0005)." (PMID 35105856, 2022).
VEXAS syndrome (2 papers, 2025). An adult-onset inflammatory disease that affects only males and is caused by somatic, not germline, mutations. "Similar patterns of co‐occurring mutations in myeloid diseases have been reported, including DNMT3A, TET2 and SF3B1 in MDS and VEXAS syndrome." (PMID 41310823, 2025).
Viral infection (2 papers, 2018 to 2024). "Viral infection, which is a major cause of HCC, did not influence anti-SF3B1 autoantibody level." (PMID 29954402, 2018).
aortic stenosis (1 paper, 2020). Aortic valve stenosis is a aortic valve disease caused by the incomplete opening of the aortic valve. "In accordance with HIF-1α induction, elevated KHK-C and SF3B1 levels were also detected in biopsies from patients suffering from aortic stenosis or hypertrophic cardiomyopathy." (PMID 32733884, 2020).
Arrhythmia (1 paper, 2025). Any cardiac rhythm other than the normal sinus rhythm.
breast adenocarcinoma (1 paper, 2017). "In both TCGA breast adenocarcinoma data and the Cancer Cell Line Encyclopedia, SF3B1neutral samples exhibited significantly higher expression of SF3B1 mRNA relative to SF3B1loss samples (Mann-Whitney p<10−4, for both datasets), suggesting excess mRNA over requirements for survival." (PMID 28177281, 2017).
CNS melanoma (1 paper, 2016). "The other mutation in codon 625 of SF3B1 (c.1874G > A (p.(Arg625His))) was present in a CNS melanoma of a 31-year-old woman (patient #21)." (PMID 26769193, 2016).
co-infection (1 paper, 2015). "Since Ad5 infection induced PHF5A and SF3B1 displacement, it is plausible that Ad5 co-infection increases expression from AAV vectors, at least in part, through U2 snRNP inhibition." (PMID 26244496, 2015). "Although human adenovirus 5 (Ad5) co-infection alone enhanced AAV2 transduction 30-fold, dual treatments of Ad5 co-infection and SF3B1 knockdown showed minimal additive effects on AAV transduction." (PMID 26244496, 2015). "In contrast, dual treatments with Ad5 co-infection and SF3B1 inhibition showed no additive effect, suggesting a common target shared by Ad5 and SF3B1 inhibition." (PMID 26244496, 2015).
erythroleukemia (1 paper, 2022). Acute erythroid leukemia characterised by the presence of at least 50% erythroid precursors and at least 20% myeloblasts in the bone marrow. "To investigate the functional consequences of mutations in SF3B1, we used the CRISPR/Cas9 genome engineering method to introduce the hotspot K700E mutation in K562 cells, an erythroleukemia cell line commonly used as a model in MDS and AML." (PMID 35478057, 2022).
Ewing sarcoma (1 paper, 2021). A small round cell tumor that lacks morphologic, immunohistochemical, and electron microscopic evidence of neuroectodermal differentiation. "Silencing SF3B1 or SF3A1 reduced EWS-FLI1 protein activity and Ewing sarcoma cell survival; and inhibition of SF3B1 with a small molecule resulted in mis-splicing of EWS-FLI1 and loss of Ewing sarcoma cell viability." (PMID 34065983, 2021).
iris tumours (1 paper, 2020). "As in UM, mutations in BAP1, EIF1AX and SF3B1 are frequently seen in iris tumours." (PMID 32998469, 2020).
iron metabolism disorders (1 paper, 2023). "Existing studies on the pathophysiological mechanisms of SF3B1 mutations in MDS have focused on impaired erythropoiesis, iron metabolism disorders, hyperinflammatory features, and R-loop accumulation, which constitute the significant clinical features of MDS." (PMID 37007111, 2023).
marginal zone lymphoma (1 paper, 2019). A usually indolent mature B-cell lymphoma, arising from the marginal zone of lymphoid tissues. "MYD88 mutations areslightly more frequent in marginal zone lymphoma (MZL) than CLL, but one of these two patients also harbored an SF3B1 mutation, which is far more frequent in CLL." (PMID 31590326, 2019).
melanocytic nevus (1 paper, 2016). A neoplasm composed of melanocytes that usually appears as a dark spot on the skin. "The observation that the SF3B1 mutation was not present in the melanocytic nevus of this patient suggests that it indeed plays a role later on in tumorigenesis." (PMID 26769193, 2016).
metastatic melanoma (1 paper, 2022). A melanoma that has spread from its primary site to another anatomic site. "We also found that BRAF class 1 mutations (20.3% vs. 5.8%) were more frequent in metastatic melanomas, while SPRED1 inactivation (3.9% vs. 19.8%), SF3B1 mutations (1.6% vs. 9.3%), and amplifications of CRKL (6.3% vs. 17.4%) and MAPK1 (1.6% vs. 11.6%) were more frequent in primary samples." (PMID 35706047, 2022).
Nager syndrome (1 paper, 2025). Nager syndrome, also called Nager acrofacial dysostosis (NAFD) is a congenital malformation syndrome characterized by mandibulofacial dystosis (malar hypoplasia, micrognathia, external ear malformations) and variable preaxial limb defects. "For instance, SF3B1 mutations cause skeletal abnormalities, while SF3B4 mutations lead to Nager syndrome." (PMID 40608414, 2025).
neurocutaneous melanocytosis (1 paper, 2016). Neurocutaneous melanocytosis (NCM) is a rare congenital neurological disorder characterized by abnormal aggregations of nevomelanocytes within the central nervous system (leptomeningeal melanocytosis) associated with large or giant congenital melanocytic nevi (CMN). "Furthermore, like in UMs, in two cases the SF3B1 mutation co-occurred with a GNAQ or GNA11 mutation, while in a third case (with neurocutaneous melanocytosis) an NRAS mutation was present." (PMID 26769193, 2016).
non-small cell lung carcinoma (1 paper, 2024). A group of at least three distinct histological types of lung cancer, including non-small cell squamous cell carcinoma, adenocarcinoma, and large cell carcinoma. "Additionally, Sf3b1 is involved in the prognosis of non-small-cell lung carcinoma." (PMID 39220589, 2024).
ocular melanoma (1 paper, 2021). A melanoma that arises from the structures of the eye or ocular adnexa. "In conclusion, based on our molecular findings, CM comprises a separate entity within the ocular melanoma group, although there certainly are overlapping molecular features with UM, such as the presence of BAP1 and SF3B1 mutations." (PMID 34071371, 2021).
Pancytopenia (1 paper, 2023). An abnormal reduction in numbers of all blood cell types (red blood cells, white blood cells, and platelets). "This indicates that the SF3B1 mutation triggers pancytopenia in the cells and then the JAK2 mutation is acquired as a second-hit mutation, causing thrombocytosis in the patient to rescue the pancytopenia to some extent." (PMID 37629188, 2023).
papillary carcinoma (1 paper, 2015). A malignant epithelial neoplasm characterized by a papillary growth pattern. "Given the higher frequency of SF3B1 K700E mutations in papillary carcinomas of the breast, we hypothesised that these mutations may underpin their biology and may be present at additional hotspots and/or be sub-clonal in the ‘wild-type’ samples." (PMID 25424858, 2015). "Taken together, our findings demonstrate that although SF3B1 mutations are unlikely to account for the histological characteristics of papillary carcinomas of the breast, these mutations affect mRNA splicing and likely constitute driver genetic events." (PMID 25424858, 2015).
pituitary tumor (1 paper, 2022). A benign or malignant neoplasm affecting the pituitary gland. "To verify the effect of mutant SF3B1 on DLG1 in vitro, we infected primary cultured pituitary tumor cells with adenovirus carrying the SF3B1-R625H mutation, and the results showed that the cryptic DLG1 transcript was observed in the Ad-SF3B1-R625H group." (PMID 35039052, 2022).
prolactinomas (1 paper, 2025). "Seven haplotypic variants of SF3B1 may be associated with aggressive tumor behavior and poor clinical outcomes in prolactinomas." (PMID 40718389, 2025).
retinal degeneration (1 paper, 2024). Degeneration of the retina. "A further large group of su(rdgB) belong to those regulating transcription (XNP, Fne, Yeti, TFIIFβ, TFIIEα, CG33017, Set, CG7839), and Sf3b1, Cmtr1, Rpl10Ab, TFIIFβ, and Sas10 were among those candidates that in addition suppressed retinal degeneration in norpAp24." (PMID 38499328, 2024).
Sepsis (1 paper, 2025). Sepsis is defined as life-threatening organ dysfunction caused by a dysregulated host response to infection. "Notably, six of these genes, including GSPT2, SMCHD1, SF3B1, DDX3X, and F3, showed significant differences and consistent trends between sepsis and septic ARDS samples in the GSE66890 and GSE32707 databases." (PMID 39854144, 2025).
spinal muscular atrophy (1 paper, 2020). A motor neuron disease that affect the muscles, and characterized by muscle weakness and atrophy resulting from progressive degeneration and irreversible loss of the anterior horn cells in the spinal cord (i.e., lower motor neurons) and the brain stem nuclei. "RT-PCR analysis of SMN exon 7 splicing in SF3B1 KD or overexpressed HCT116, SH-SY5Y, HEK293T, and spinal muscular atrophy (SMA) patient cells validated the results." (PMID 33317029, 2020).
T-cell leukemia (1 paper, 2022). A malignant disease of the T-lymphocytes in the bone marrow, thymus, and/or blood. "The splicing factor SF3B1 is regulated at the protein level and is a therapeutic target in T cell leukemia." (PMID 35061527, 2022).
testicular germ cell tumor (1 paper, 2025). A germ cell tumor arising from the testis. "This region, commonly altered in several cancer types (especially testicular germ cell tumors), contains four NMD-related genes (CWC22, SF3B1, NOP58, and FARSB)." (PMID 41023738, 2025).
uveal cancer (1 paper, 2024). A primary or metastatic malignant neoplasm that affects the choroid, ciliary body, or iris. "Recently, SF3B1 mutations in breast and uveal cancers were associated to metabolic dysregulation, characterized by a decrease in OXPHOS." (PMID 38517966, 2024).
cancer (229 papers, 2014 to 2026). A tumor composed of atypical neoplastic, often pleomorphic cells that invade other tissues. "Together, our study reveals a novel mechanism by which SF3B1 mutation influences cancer progression via circRNA, and underscores the important role of MYH9 in organization of nuclear actin network." (PMID 41864997, 2026). "We focused on de novo SF3B1 missense variants, which were largely distinct from those reported in cancer." (PMID 41577671, 2026). "In cancer, recurrent mutations in splicing factors such as SF3B1, SRSF2, and U2AF1 are frequently observed, and these aberrations likely induce translational dysregulation associated with ORF dominance." (PMID 41596295, 2026). "SF3B1 mutations are known to promote aberrant splicing and are associated with cancer, particularly the lysine 700 to glutamate mutation (K700E)." (PMID 42239186, 2026). "While cancer-associated SF3B1 mutation leads to impaired DNA repair, the underlying mechanism remains elusive." (PMID 41864997, 2026). "We assessed the expression of the SF3B1, a core component of the spliceosome, which is essential for the proper splicing of pre-mRNA and is implicated in cancer progression." (PMID 41009559, 2025). "Recurrent somatic mutations in the key spliceosome component, SF3B1, have been identified at various frequencies across several cancer types." (PMID 40595498, 2025). "SF3B1 mutation accelerates cancer progression through alternative RNA splicing in various cancer types by activating the Akt and NF-κB pathway, MYC activation, inflammation pathway, and TGF-β signaling in several cancers." (PMID 40694421, 2025). "It further delineates how AS influences cell development, immune modulation, and stress adaptation, while its dysregulation contributes to human pathologies, including SF3B1 mutant cancers, TDP‐43‐associated neurodegeneration, and cardiovascular disease." (PMID 41399527, 2025). "In numerous cancer cells, SF3B1 mutations have been shown to disrupt various cellular processes, such as heme metabolism, immune surveillance, DNA damage maintenance, and Notch signaling." (PMID 40158006, 2025). "Our studies of SF3B1 function in a non-cancer cell line provides further insights into how this mutation alters the dynamics of RNA Pol II and mature mRNA output." (PMID 41406100, 2025). "Together, these results suggest that SF3B1 mutation uses aberrant RNA splicing to promote tumorigenesis via regulation of tumor-specific pathways, serving as a unique vulnerability in cancers with these mutations." (PMID 40694421, 2025). "Pan-cancer genome analyses indicate that heterozygous SF3B1 mutations are primarily associated with hematological cancers, however, the fitness advantage these mutations provide to cancer cells is poorly understood." (PMID 41406100, 2025). "SF3B1, a component of the U2 snRNP pre-mRNA splicing factor, plays a critical role in splicing and is frequently mutated in cancer, particularly hematologic malignancies." (PMID 41406100, 2025). "Hotspot mutations in SF3B1 (splicing factor 3b subunit 1) have been observed in a variety of cancers and these mutations result in a large number of aberrant mRNA splices, which are strongly associated with tumorigenesis." (PMID 40630951, 2025). "Among its seven components, SF3B1 is considered the most commonly mutated splicing factor across cancers." (PMID 38671459, 2024). "Hotspot mutations on SF3B1 drive cryptic 3′ splice site selection, rewiring cellular splicing circuitries and promoting oncogenesis in a variety of cancers." (PMID 39194178, 2024). "Despite SF3B1 being the most recurrently mutated splicing gene in cancers, there exist remarkably few isogenic cell lines modeling for SF3B1 mutation in the appropriate disease contexts." (PMID 39194178, 2024).
cancer (continued). "The most common cancer-associated mutations in SF3B1 (K700E, R625*, K666*) are located in the protein’s C-terminal HEAT repeats, and recent work has shown that these amino acids cluster into a pocket where the cofactor SUGP1 sits." (PMID 39316554, 2024). "SF3B1 plays a key role in the spliceosome assembly and is the most commonly mutated spliceosomal gene across cancers, including MDS." (PMID 38997434, 2024). "The splicing factor which has been found to be most commonly mutated in different cancers is the Splicing Factor 3b Subunit 1 (SF3B1)." (PMID 38731892, 2024). "Since exon 15 inclusion in BRD9 has been reported to lead to nonsense-mediated decay and lower transcript levels in UVM and MDS, we sought to investigate BRD9 gene expression levels in additional cancer types that harbor SF3B1 mutations." (PMID 39261602, 2024). "Our results highlight the impact of cancer-associated SF3B1 mutation on immune responses, which affect cancer development." (PMID 39303038, 2024). "In vitro cell line systems are therefore an attractive orthogonal model for the functional and mechanistic dissection of SF3B1 mutation owing to the ease of engineering and broad representation from across the cancer spectrum." (PMID 39194178, 2024). "Our approach provides new insights on the role of SF3B1 mutation in cancer and enables the generation of SF3B1 mutant cell lines in relevant cellular context." (PMID 39194178, 2024). "The loss of interaction between SF3B1 and SUGP1 due to cancer mutations in either SF3B1 or SUGP1 provides an explanation for why the mutant spliceosome fails to activate DHX15 for ATP hydrolysis required for canonical branch site selection." (PMID 37977822, 2023). "We retrieved the target articles and investigated the association between SF3B1 and the mentioned four types of cancer." (PMID 36792691, 2023). "We want to extend this study by considering a longer period and more cancer types in addition to other diseases and mutations associated with SF3B1." (PMID 36792691, 2023). "The authors queried 20 cancer types with at least one SF3B1 mutation to identify intronic sequences, which were strongly predicted to be recurrently mis-spliced via the use of cryptic 3’ splice sites." (PMID 37510283, 2023). "Somatic mutations of SF3B1 were shown to be associated with aberrant splicing, producing abnormal transcripts that drive cancer development and/or prognosis." (PMID 36792691, 2023). "Several mutations in splicing factors are linked to cancer, such as SF3B1 (splicing factor 3b subunit 1), a gene that encodes the subunit 1 of splicing factor 3b, which is the most frequently mutated RNA splicing factor in cancer." (PMID 36609432, 2023). "Other splicing inhibitors such as sudemycin D6 or E7107 also display stronger cytotoxic effects on splicing factor–mutant cancer cells, including mutations in SF3B1 and other splicing factors such as U2AF1 and SRSF2." (PMID 37562845, 2023). "SF3B1 exhibits almost exclusively heterozygous missense mutations in cancer, and its high proportion in hematopoietic malignancies such as MDS occurs within codon 700 (K700E) located in the HEAT domain repeat sequence." (PMID 37007111, 2023). "We have shown that numerous SUGP1 mutations affecting residues critical for binding SF3B1 recapitulate the splicing defects of hotspot SF3B1 cancer mutations, confirming the cooperative role of these two proteins in 3′ss selection." (PMID 37977822, 2023). "SF3B1 is the most frequently mutated spliceosomal protein in several cancers and is a major drug target." (PMID 36855776, 2023). "Transcriptomic analyses revealed that cancer-associated SF3B1 mutations are generally associated with the usage of alternative 3’ (a3′ss) ~10–30 nucleotides upstream of the canonical 3’ss." (PMID 37510283, 2023). "SF3B1 recognizes the branch site adenosine and SF3B1 mutations identified in cancer cells promote the usage of cryptic 3’ss located 10–30 nucleotides upstream of the canonical 3’ss." (PMID 37562845, 2023).